IL1B (interleukin 1 beta)
Diseases named in the same sentence as IL1B in open-access papers (continued):
Sharing a sentence is not in itself a finding about the gene and the disease.
sleep disorder (25 papers, 2010 to 2026). A change from the patient's baseline sleeping pattern, in the hours slept and/or an alteration/dysfunction in the stages of sleep. "The study aimed to elucidate the relationship between CSF IL-1β, smoking, and their effects on sleep given both inflammatory factors and smoking have been associated with sleep disorders in recent studies." (PMID 40235833, 2025). "Inflammatory factors and cigarette smoking have been associated with sleep disorders but molecular mechanisms that regulate sleep, specifically the role of interleukin-1β (IL-1β), remain controversial." (PMID 40235833, 2025). "In the present study, we assessed interleukin (IL)-1β and APOEε4 polymorphisms for association with susceptibility of sleep disturbances in AD patients." (PMID 26937653, 2016). "However, the association between IL-1β and sleep disorders, as well as the upregulation of CSF IL-1β, remains inconclusive." (PMID 40235833, 2025). "Sleep disorders are also associated with an increased systemic immune and inflammatory dysregulation, mainly due to hyperexpression of pro-inflammatory mediators and cytokines (e.g., IL-1β, IL-2, IL-6, TNF-α, IL-18, sTNF-R1, and sTNF-R2), and intermittent hypoxia-induced oxidative stress." (PMID 41156291, 2025). "Thus, our data indicate that the IL-1β-31TT genotype and the APOEε4 allele were associated with sleep disturbances in AD patients and that these two SNPs synergistically enhanced LPS-induced IL-1β, IL-6 and TNF-α overexpression in white blood cells from AD patients with sleep disturbances." (PMID 26937653, 2016). "Elevated levels of IL-1β and TNF-α have been linked to various sleep disorders, such as sleep apnoea and chronic insomnia." (PMID 40254933, 2025). "While there is no concrete conclusion about alterations in serum inflammatory factors in MDD patients experiencing sleep disturbances, IL-1β seems to be central to this process according to this research." (PMID 37692303, 2023). "Previous studies have also reported elevated levels of IL-2 and IL-1β upon improved sleep and an elevation in IL-10 levels upon sleep disorders." (PMID 37139438, 2023). "Sleep disorders promote a low-grade inflammatory status by increasing circulating proinflammatory cytokines (IL-1β, IL-6, IL-17A, TNF-α) and CRP." (PMID 30402295, 2018). "Moreover, sleep disorders impair the immune response and cause systemic inflammation by the dysregulation of substances such as TNF-α, IL-1β, and IL-6." (PMID 36188174, 2022). "In addition, sleep disorders also increase the levels of cytokines such as IL-1, IL-1β, IL-6, IL-17, and TNF-α." (PMID 33679706, 2020). "IL‐1β might, through melatonin and vice versa, determine sleep disorders too." (PMID 33295155, 2021). "Patients with sleep disorders due to acute cerebral infarction displayed increased inflammatory factors, including C-reactive protein (CRP), IL-6, IL-1β, TNF-α and Hcrt, compared with normal levels." (PMID 38671959, 2024). "Sleep disorders, including RBD and ESS, exhibit significantly altered levels of IL-6, CRP, IL-1β, sTREM2, CCL3 and NO, suggesting these markers represent potential markers in PD patients." (PMID 36739284, 2023). "Increased gut microbiota-derived lipopolysaccharide (LPS) contributes to the production of proinflammatory cytokines such as IL-1β, TNF-α, and IL-6, which have been shown to play a key role in sleep disturbances." (PMID 36190400, 2022). "In a previous animal experiment, IL–1β level was increased in hypothalamus of mice with REM sleep deprivation, implying a potential role of neuroinflammation on sleep disorders." (PMID 26431210, 2015). "Studies have found that patients with sleep disturbance show altered circulating concentrations of TNF-α, IL-1β, and IL-1." (PMID 21034496, 2010).
sleep disorder (continued). "Effectively, IL1-β and TNF-α, which increase in the serum of animals in OSA models and in that of patients with this sleep disorder, have proved to increase the adhesion of MSC to cardiac endothelial cells both in vivo and in vitro." (PMID 20604943, 2010). "After several days of sleep deprivation, IL-1β levels in the blood increase.To date, studies on the relationship between the salivary concentration of IL-1β and sleep disorders have not shown increased values for IL-1β." (PMID 39585035, 2024). "These bidirectional associations could be equally mediated by proteins, such as BDNF (brain-derived neurotrophic factors) or proinflammatory cytokines (IL-1β, TNF-α), which are involved in both pain perception and sleep disorders." (PMID 34574901, 2021).
viral myocarditis (25 papers, 2013 to 2025). Myocarditis that is caused by an infection with a viral agent. "In the current study, we found that NLRP3 inflammasome was highly expressed in viral myocarditis with increased levels of IL-18 and IL-1β." (PMID 36418383, 2022). "Previous investigations showed that the neutralization of IL-1β with an IL-1β receptor antagonist could decrease myocardial injury in a murine model of viral myocarditis." (PMID 25462010, 2014). "Inflammatory processes induced by viral infection are considered an important pathogenic mechanism in acute myocarditis or DCM, and tumor necrosis factor (TNF)-α and interleukin (IL)-1β may be the dominant inflammatory cytokines expressed in viral myocarditis." (PMID 25462010, 2014). "It reduces ROS production and the secretion of IL-1β to alleviate inflammation associated with metabolic disturbance in murine RAW 264.7 or J774A.1 macrophages; it suppresses plasma TLR4 expression and myocardium inflammatory cell infiltration from mice with viral myocarditis." (PMID 35774377, 2022). "Upregulation of pro-inflammatory cytokines, such as IL-1β, TNF-ɑ, and IFN-ɣ, has also been demonstrated in vivo in several mouse models of acute viral myocarditis." (PMID 40146392, 2025). "All of the miRs enriched in PEV had reported roles in the literature that inhibited specific pathways known to be involved in the pathogenesis of viral myocarditis including reducing viral replication, TLR4 signaling, inflammasome/NLRP3, and IL-1β." (PMID 39835120, 2024). "Lupeol downregulated the mRNA and protein expressions of TLR4 with the inhibition of the downstream MyD88 and NF-κB, restraining the release of IL-1β and TNF-ɑ, in viral myocarditis mice." (PMID 34777686, 2021). "Th1 cells and their proinflammatory cytokines, such as IL-1β and TNF-α, were shown to be etiological factors in the induction of viral myocarditis." (PMID 34452454, 2021). "In CVB3-induced viral myocarditis, IL-37 treatment obviously weakened the upregulation of NLRP3 inflammasomes (NLRP3, ASC, and caspase-1), and the activation of NLRP3 inflammasomes as evidenced by decreased inflammatory mediators (IL-1β and IL-18)." (PMID 36418383, 2022). "Finally, nicotine treatment reduced inflammatory cytokines (IL-1β, IL-6, and TNF-α) in the myocardium, ameliorated the necrosis of cardiomyocytes and cellular infiltration in mice with viral myocarditis." (PMID 30176160, 2018). "From this, we speculated that the cholinergic anti-inflammatory pathway did not affect the production and release of IFN-γ in viral myocarditis, the reduction in the inflammatory response was through the down-regulation of IL-1β, IL-6, and TNF-α, not IFN-γ." (PMID 28197102, 2017).
astrocytoma (24 papers, 2011 to 2025). "In summary, our study demonstrates that dysregulation of the TNF-α signaling axis—including upregulation of TNF-α, IL-1β, and MAP3K8—is a hallmark of high-grade astrocytomas and correlates with worse patient outcomes." (PMID 40565357, 2025). "Results and Conclusions: ET-1 secretion by astrocytoma cells was only stimulated by the pro-inflammatory cytokines IL-1β and TNF-α." (PMID 31969819, 2019). "We found that ET-1 secretion in human astrocytoma cells was stimulated by the pro-inflammatory cytokines IL-1β and TNF-α, which are known to be present in focal MS lesions." (PMID 31969819, 2019). "The results showed that WSC was able to inhibit the expression of TNF-α, IL-6, and iNOS in human astrocytoma cells stimulated by IL-1β or Aβ peptide." (PMID 30060500, 2018). "Consistent with our findings, LPS exposure induces release of IL-1β and IL-6 in U373-MG human astrocytoma cells." (PMID 28881826, 2017). "We compared protein levels with Western blotting analysis, and we investigated CK2 activity in human U373 astrocytoma cells and human primary adult astrocytes stimulated with IL-1β or TNF-α." (PMID 26732432, 2016). "The astrocytoma cell lines U251 was stimulated with IL-1β and IFN-γ for 48 h and kif21b expression was compared between unstimulated and stimulated conditions." (PMID 25274010, 2014). "We confirmed IL-1β expression in tumor cells, of both low- and high-grade astrocytomas, in agreement with the notion that astroglial cells represent a main source of brain IL-1β." (PMID 23270518, 2012). "A human astrocytoma cell line (U87-MG) was activated with IL-1β and transfected with firefly luciferase constructs containing a 929 bp fragment representing the distal CCL2 promoter with either the -2578 A allele or the -2578 G allele." (PMID 21760952, 2011). "Our data suggest that the inflammatory mediators, especially IL-1β, may prime naïve cells to infection and lead to increased infection rates in microglial and astrocytoma cells." (PMID 30101649, 2018). "Furthermore, human astrocytoma cells were challenged with 0, 1, 10, 100, or 500 ng/ml of IL-17 for 24 h, and then the production of pro-inflammatory cytokines IL-1β, IL-6 and TNF-α were determined by ELISA." (PMID 28281545, 2017). "Our findings substantiate a model for T cell exclusion in IDHmt astrocytoma in which microglia produce SPP1 and IL-1β, thereby enabling crosstalk with CD44 and IL-1R-positive GTCs, a process that is highly reminiscent of glial scarring." (PMID 39880824, 2025). "In fact, significant upregulations of MYD88, SRF, JUN, IL1B, TRIF, RIPK1, NLRP3 were detected in GBM cases compared to lower grade astrocytomas (AGII and AGIII)." (PMID 33446690, 2021). "The selective CK2 inhibitor CX-4945 significantly reduced the IL-1β/TNF-α induced secretion of the inflammatory cytokines MCP-1 and IL-6 both in human primary astrocytes and U373 astrocytoma cells in a dose-dependent manner." (PMID 26732432, 2016). "Our transcriptomic data of U87MG cells 12 h after LPS stimulation and the TCGA RNASeq dataset of astrocytoma showed upregulation of genes related to inflammasome and ripoptosome pathways, namely MYD88, NLRP3, RIPK1 and RIPK3, and also SRF, JUN and IL1B, the downstream regulated genes." (PMID 33446690, 2021). "So far, pro-inflammatory factors such as LPS or IL-1β and TNFα were reported to upregulate PTPRG in astrocytoma cell line or astrocyte culture and also appear to associate to specific myeloid lineages, such as the differentiation of monocytes to dendritic cells." (PMID 35071225, 2021). "However, we recently showed that the pro-inflammatory cytokines IL-1β and TNF-α, which are present in active inflammatory MS plaques, stimulated ET-1 secretion in cultured human astrocytoma cells." (PMID 32765401, 2020). "IL-1β protein production was observed in GBM cells but not in low grade astrocytoma cells." (PMID 25054228, 2014).
bronchiectasis (24 papers, 2007 to 2026). Segmental, irreversible dilation of the bronchial tree resulting in the accumulation of secretions which leads to obstruction. "However, compared to sputum from healthy controls, PCD sputum contained elevated IL-1β levels, a pro-inflammatory cytokine predominantly produced by M1 macrophages that is linked to disease severity and neutrophilic inflammation in patients with bronchiectasis." (PMID 41582098, 2026). "In our study, NETs resulted in excessive IL-1β secretion in bronchiectasis patients, and LPS + NET costimulation more prominently activated inflammasomes, indicating that NETs constitute the core secondary signal for inflammasome activation in bronchiectasis." (PMID 41395250, 2025). "A previous study analyzed IL-1β levels and airway microbiota in patients with bronchiectasis, finding a correlation between the relative abundance of Proteobacteria and IL-1β." (PMID 41011430, 2025). "A recent study of bronchiectasis revealed that IL-1β–expressing macrophage is upregulated in bronchiolar mucus plugs, whereas mucus plugs in the central airways are filled with eosinophils and Charcot-Leyden crystals in ABPA." (PMID 39659740, 2025). "In patients with bronchiectasis, the presence of Rothia was found to be negatively correlated with pro-inflammatory factors such as IL-8, IL-1β, MMP-1, MMP-8, and MMP-9 in sputum." (PMID 38779669, 2024). "In a cohort of adults with bronchiectasis, the abundance of Rothia species was negatively correlated with pro-inflammatory markers (interleukin (IL)-8 and IL-1β) and matrix metalloproteinase (MMP)-1, MMP-8 and MMP-9 in sputum." (PMID 36403054, 2022). "In contrast, the levels of IL-1β were significantly higher in the bronchiectasis group than in the control group." (PMID 33886789, 2021). "Proinflammatory cytokines, such as TNF-α, IL-6, IL-8, and IL-1b, were studied, as they have been found elevated in sputum or bronchoalveolar damage in bronchiectasis patients." (PMID 32823681, 2020). "Infection with Pseudomonas aeruginosa (PsA), one of the most clinically relevant pathogens in CF bronchiectasis, can lead to an increase in levels of IL-1β in BAL fluid from these patients." (PMID 30380761, 2018). "Th17 pathway cytokines were quantified in bronchoalveolar lavage fluid (BALF), and gene expression of IL-17A, IL-1β, IL-8 and IL-23 determined from endobronchial biopsies (EBx) in 41 stable bronchiectasis subjects and 20 healthy controls." (PMID 25822228, 2015). "Bronchiectasis patients with high sputum IL-1β levels reportedly exhibit greater disease severity." (PMID 41395250, 2025). "Overall, increased sputum IL-1β expression levels could differentiate AE from stable state and reflect blood neutrophilia in bronchiectasis." (PMID 41395250, 2025). "There were significant differences in cytokine (IL-8, IL-1β, IL-6, TNF-α, IL-12) levels of BAL fluid between patients with bronchiectasis and healthy controls." (PMID 17224076, 2007). "The BAL fluid levels of the cytokines (IL-8, IL-1β, IL-6, TNF-α, IL-12) were found to be significantly elevated in patients of bronchiectasis when compared with controls (p < 0.0001)." (PMID 17224076, 2007). "While hs-CRP has been assessed in this study for its role in predicting bronchiectasis exacerbation, other inflammatory markers such as plasma IL-1β, IL-8, TNF-α, and LTB4 were not examined as they were not routinely available in our centre." (PMID 38350918, 2024). "Airway secretions of non-CF bronchiectasis patients with Pseudomonas or other chronic infection contain higher levels of IL-1β which is a powerful proinflammatory cytokine stimulating osteoclastogenesis and increasing in vitro and in vivo bone loss." (PMID 30717716, 2019). "The current data demonstrate highly significant increases in all Th17 pathway-associated chemokines and cytokines measured in the airways of adult bronchiectasis subjects, including pathway effectors (IL-17A, IL-6, IL-8 and TNF-α) and regulators (IL-1α, IL-1β, IL-6 and IL-23)." (PMID 25822228, 2015).
bronchiectasis (continued). "Therefore, we aimed to evaluate acute systemic levels of proinflammatory cytokines (IL-17a, IL-1β, IL-8, and tumor necrosis factor alpha (TNF-α)) and high-sensitivity C-reactive protein (hsCRP) during bronchiectasis exacerbations and follow-up (days 30 and 60)." (PMID 32823681, 2020). "Bacterial load in non-CF bronchiectasis has been correlated with increases in airway (NE, IL-8, IL-1β and TNF-α) and systemic (ICAM-1, E-selectin) derived inflammatory markers, phenomena confirmed in vitro using bronchial epithelial cell lines treated with sputum from bronchiectasis patients." (PMID 29788954, 2018). "However, while gene expression of both IL-1β and IL-8 was significantly upregulated in the bronchial mucosa of non-CF bronchiectasis subjects, IL-17A was not, possibly reflecting the scarce relative abundance of the cells of origin in the mucosa." (PMID 25822228, 2015). "Notably, several studies have reported increased macrophage numbers in bronchiectasis and a recent study demonstrated that mucus plugs in non-cystic fibrosis bronchiectasis are populated by IL-1β-producing macrophages, indicating a central role for macrophages in the pathogenesis of bronchiectasis." (PMID 41582098, 2026). "Compared to normal controls, subjects with non-CF bronchiectasis also had highly significantly elevated BALF levels of all measured Th17 pathway cytokines (IL-1α, IL1β, IL-6, IL-8, IL-23 and TNF-α (p<0.0001 for all)." (PMID 25822228, 2015). "The most comprehensive BALF study in adult non-CF bronchiectasis demonstrated increased levels of neutrophil elastase, myeloperoxidase, TNF-α, IL-6 and IL-8 but not IL1β compared to controls." (PMID 25822228, 2015).